CD28 (CD28 molecule)
Diseases named in the same sentence as CD28 in open-access papers (continued):
Sharing a sentence is not in itself a finding about the gene and the disease.
HCMV infection (12 papers, 2019 to 2025). "Finally, HCMV infection has been positively associated with CD4+CD28- T-cell expansion and high cardiovascular disease (CVD) mortality risk among RA patients, further confirming a direct causal link between HCMV and vascular damage in AD." (PMID 33567734, 2021). "The results showed that activation of PBLs with CD3/CD28 stimulation reduced T-cell killing of GC cells upon HCMV infection (Mean ± SEM: 46,676 ± 3,403 in the AD169 infected group vs. 27,786 ± 1,552 in the uninfected group, P < 0.001)." (PMID 39934685, 2025). "Recent studies have confirmed that the terminally differentiated T cells and its CD28- subsets have the potential to serve as a biomarker of immunosenescence in the context of cytomegalovirus infection." (PMID 38755605, 2024). "Effect of HCMV infection on cytokine responses to T cell stimulation with aCD3/CD28 at 9 months of age." (PMID 32582177, 2020). "Further work is required to characterise these T cells with regard to other co-stimulatory molecules, especially CD28, in the context of CMV infection." (PMID 30984377, 2019). "In this study, we found that CD3/CD28-activated Jurkat cells could also be used to mimic the immune response of in vivo native T cells to HCMV infection." (PMID 38829126, 2024). "Intriguingly, HCMV infection is a major trigger of CD4+CD28− T-cells expansion." (PMID 33567734, 2021). "In this study, we explored the association between donor SNPs of co-stimulatory genes (CTLA4, CD28, TNFSF4, and PDCD1) and the mortality, CMV infection, GVHD, and relapse of their corresponding recipients in the Taiwanese population." (PMID 34671352, 2021). "In fact persistent HCMV infection leads to chronic stimulation of CD8 T cells, which expand clonally showing an effector memory phenotype characterized by low CD28 expression." (PMID 31608061, 2019). "Considering the time course of infection, the expression of CD27 and CD28 was progressively lost after HCMV infection to reach a stable CD27-/CD28-, CCR7-, CD45RA+, CD8+ TEMRA phenotype during chronic infection such as in HV hosts with a latent HCMV infection." (PMID 36532017, 2022). "With the importance of co-stimulatory signals in the immune system and transplantation tolerance, the associations of the four co-stimulatory genes including CTLA4, TNFSF4, CD28, and PDCD1 with the mortality, relapse, CMV infection, and GVHD after HSCT were analyzed in this study." (PMID 34671352, 2021). "In this study, we investigated further whether these is an association between 34 donor SNPs in the four co-stimulatory genes (TNFSF4, CTLA4, CD28, and PDCD1) and the occurrence of adverse outcomes (mortality, relapse, CMV infection, and GVHD) for patients with AML and ALL." (PMID 34671352, 2021). "Also, cytomegalovirus infection has decreased CD8 activity by affecting CD28 signaling, and mice lacking CD28 have higher cytotoxic responses." (PMID 39123358, 2024).
lymphopenia (12 papers, 2010 to 2025). Reduction in the number of lymphocytes. "CD28-mediated co-stimulation appears to influence T cell susceptibility to activation-induced cell death, which may play a role in lymphopenia." (PMID 40310166, 2025). "Patients with GOF mutations in STING frequently display lymphopenia and intrinsic defects in anti-CD3/CD28 T cell proliferation, as observed in our patient." (PMID 38953896, 2024). "Of note, markers of immune aging have been documented in the ADs in humans, such as reduced percentage of TREC+ cells and/or lymphopenia, LIP in T cell subsets, and loss of CD28+ cells/accumulation of CD28null cells in T cell subsets." (PMID 33923792, 2021). "In addition to lymphopenia, other markers involving immune aging have been demonstrated in severe and extremely severe COVID-19 patients including decreased CD28 expression and increased CD45RO (memory phenotype) expression on CD4+ and CD8+ T cells." (PMID 33923792, 2021). "RTEs, Naïve and central memory CD4 cells, were also severely reduced in ESRD compared to controls, while CD4+CD28- cells were significantly increased, despite the general CD4 lymphopenia." (PMID 35615367, 2022). "Given that CD28 and IL-2 play important roles in Treg function, the relationships between premature CD4+ T cell aging and lymphopenia as well as Treg defects in autoimmune-prone NOD mice are proposed." (PMID 24586733, 2014). "Unfortunately, the therapeutic potential of agonists of the CD3/CD28/CD2 signaling pathway is uncertain, given the plethora of undesirable side effects, including transient lymphopenia, previously observed in patients treated with OKT3 antibodies." (PMID 24385908, 2013). "Importantly, we observed markedly decreased expression of the major T-cell costimulatory molecule CD28 on both CD8 and CD4 T cells which together with the marked CD4 lymphopenia could be causal factors in the inadequate cell-mediated immune responses that frequently complicate the course of TB." (PMID 22567259, 2010). "CD28+, CD95+) were all diminished in recipients with lymphopenia three years after KTx." (PMID 40612959, 2025). "This activation appears to be Ag-driven and not merely the result of lymphopenia-induced activation as 1) it occurs months after engraftment, and 2) the presence of many CD28- T cells, which are the result of late-stage Ag-activation (data not shown)." (PMID 33854497, 2021).
multiple myeloma (12 papers, 2013 to 2025). "Furthermore, basophils, the CCR5+ EM3 CD4 and CD28+ EM5 CD4 subsets were increased in AL amyloidosis compared to MM." (PMID 31462637, 2019).
Arthritis (11 papers, 2009 to 2024). Inflammation of a joint. "Several studies demonstrated that CD28-mediated signaling prevented the spontaneous development of autoimmune diabetes and decreased experimental autoimmune neuritis and CD28 deficiency was highly resistant to collagen-induced arthritis in mice." (PMID 31565151, 2019). "Additionally, the presence of OX40 may neutralize costimulation of CD28, which may impair arthritis pathogenic roles of CD4+CD28+OX40+ T cells." (PMID 28320444, 2017). "Furthermore, inhibition of IL-17 prevents the development of arthritis in vaccinated mice challenged with Borrelia burgdorferi, while CD28 deficiency exacerbates joint inflammation upon Borrelia burgdorferi infection, resulting in the development of chronic Lyme arthritis." (PMID 19333372, 2009). "However, this is the first study to characterize other specific senescent biomarkers, such as CD57, PD1, NKG2D, hTERC, or p16 in CD4+CD28− cells from early arthritis patients." (PMID 33291545, 2020). "Reduced OX40 signals by MTX or Dex treatment may suppress the autoactivation of CD4+CD28− T cells and lead to arthritis remission." (PMID 28320444, 2017). "However, the absence of OX40 markedly reduced the survival of memory T cells, and late arthritis development was alleviated in the mice that received transfers with CD4+CD28+OX40− T cells." (PMID 28320444, 2017). "Furthermore, among the four T-cell subsets transferred to CIA mice, CD4+CD28−OX40+ T cells displayed the most significant pathogenic role in arthritis development compared with CD4+CD28−OX40− (P = 0.011), CD4+CD28+OX40− (P < 0.001), and CD4+CD28+OX40+ (P < 0.001) T cells." (PMID 28320444, 2017). "In this sense, VPAC2 has also been shown to be the predominant receptor in PBMC in early arthritis in different experimental conditions, such as activated memory Th cells, Th17-polarized cells, and proinflammatory CD4+CD28− T cells." (PMID 35955723, 2022). "Higher arthritis disease activity was positively correlated with CTLA4, CD28 and CD45RA and negatively correlated with CCR7 in 2019, which was a mean of about 4 years post-infection that was not conserved in 2021, which was a mean of about six-years post-infection." (PMID 38873035, 2024). "On one hand, this meant that, in early arthritis, additional mechanisms were involved in activation of CD4+CD28− T cells, except for OX40 costimulation, On the other hand, long-lived memory characteristics of OX40 may take effects in late arthritis." (PMID 28320444, 2017).
chronic lymphocytic leukemia (11 papers, 2004 to 2023). "One such example was the phase I trial failure of theralizumab, an anti-CD28 monoclonal antibody intended for use in arthritis and B cell lymphocytic leukemia (B-CLL)." (PMID 37909337, 2023). "Use of γRVs expressing second-generation anti-CD19 CARs with CD3ζ and CD28 activation domains mediated clinical responses in 6/8 patients with B cell malignancies (including chronic lymphocytic leukaemia [CLL] and follicular lymphoma)." (PMID 24935654, 2014). "In another retrospective cohort enrolling patients with CD19+ R/R NHL and chronic lymphocytic leukemia, a CAR construct containing a CD28 costimulatory domain and coexpressing truncated epidermal growth factor receptor was used to generate CD19CAR-T cells." (PMID 36176002, 2022). "The agonistic antibody binding to this receptor, theralizumab (also known as TGN1412, CD28-SuperMAB, or TAB08) was initially designed to treat B cell chronic lymphocytic leukemia (B-CLL)." (PMID 31717326, 2019). "This is in line with data published for chronic lymphocytic leukemia, where PD-1 blockade abolished the positive effect induced by anti-LAG-3 antibodies in combination with CD3/CD28 beads as a very strong stimulus." (PMID 29535740, 2018).
sarcoma (11 papers, 2015 to 2025). A usually aggressive malignant neoplasm of the soft tissue or bone. "Clinical trials evaluating CD28-based and CD28-CD3ζ-OX40 CAR T cells specifically target patients with sarcoma (e.g., NCT00902044 and NCT01953900)." (PMID 40149640, 2025). "CD28-based (NCT00902044) and CD28-CD3z-OX40 CAR T cell therapy (NCT01953900) have been used in sarcoma patients in clinical trials." (PMID 38399305, 2024). "In fact, in order to improve costimulatory signaling, CD28-based and CD28-CD3ζ-OX40 CAR T cells are being tested in clinical trials respectively on patients with sarcoma (NCT00902044 and NCT01953900)." (PMID 35433427, 2022). "Meanwhile, in a clinical trial at Baylor, patients with advanced-stage sarcoma were treated with second-generation HER2 CAR-T cells (CD28/CD3ζ) (NCT00902044)." (PMID 34839348, 2021). "A very similar CD28-CD3ζ CAR harboring the same FRP5-derived single-chain fragment variable antibody domain has been safely employed in phase I/II CAR-T clinical trials in pediatric patients with ErbB2+ sarcoma." (PMID 39963129, 2025). "In addition, DFMO and GC7 treatment sustained CD69 expression in CD8+ T cells from human sarcoma tumor infiltrating lymphocytes (TIL) following activation with anti-CD3/CD28 and IL-2." (PMID 37581943, 2023). "However, in a similar sarcoma model using TDLN which were anti-CD3/anti-CD28 activated, CD4 cells were more potent effector cells than CD8 cells." (PMID 26090481, 2015). "To evaluate the feasibility of our anti-CD137–independent and CD3/CD28 activator-based TIL expansion protocol, we collected 11 sarcoma specimens from patients who underwent surgical resection." (PMID 40145091, 2025). "Notably, CD28-based and CD28-CD3z-OX40 CAR-T-cell therapy have been used In clinical trials (NCT00902044 and NCT01953900) in sarcoma patients to enhance the costimulatory response." (PMID 36849442, 2023).
acute myeloid leukemia (10 papers, 2018 to 2025). Acute myeloid leukemia (AML) is a group of neoplasms arising from precursor cells committed to the myeloid cell-line differentiation. "Recently, a novel IFP designed to convert an inhibitory CD200R stimulus into a CD28 costimulus demonstrated how tuning different IFP domains can drastically alter the therapeutic effects in a preclinical model of acute myeloid leukemia (AML)." (PMID 37400680, 2023). "A similar phenotype was observed in dysfunctional CD8+ T cells in patients with acute myelogenous leukemia (AML) displaying co-existence of exhaustion and senescence signature characterized by reduced CD28 and CD127, high CD57 expression, and high PD-1." (PMID 35406703, 2022). "Lintuzumab-CD28/CD3ζ CD33 CAR-T immunotherapy is now under evaluation in a preclinical trial involving children and adolescents/young adults with relapsed/refractory acute myeloid leukemia (AML)." (PMID 38136311, 2023). "A second-generation CAR with a CD28 costimulatory domain demonstrated preclinical efficacy by targeting of the LeY antigen in mice bearing subcutaneous OVCAR3 ovarian cancer tumors and a clinical trial was opened to determine the efficacy in patients with acute myeloid leukemia (AML)." (PMID 34943864, 2021).
diffuse large B-cell lymphoma (10 papers, 2019 to 2025). "Noteworthy distinctions exist among these therapeutic products encompassing variances in costimulatory domain (CD28 vs. 4-1BB) and indications spanning diffuse large B-cell lymphoma (DLBCL), primary mediastinal B-cell lymphoma (PMBL), mantle cell lymphoma (MCL), and follicular lymphoma (FL)." (PMID 38473919, 2024). "In patients with diffuse large B-cell lymphoma (DLBCL), the loss of CD27 and CD28 expression in T cells correlates with the number of prior chemotherapy cycles." (PMID 38136380, 2023). "Another CD28 construct, KTE-C19 – now developed as axi-cel – designed at the NCI, was successfully employed in patients with refractory diffuse large B cell lymphoma (DLBCL) and indolent B-cell malignancies, showing a response in 12/15 cases, including 8 CR." (PMID 32477359, 2020). "For the costimulatory domains, data recently published in a meta-analysis focused on patients with diffuse large B-cell lymphoma (DLBCL) treated with CD19 CAR T cells corroborated our findings, showing higher BCR and BOR rates of CD28 (57% BCR and 81% BOR) compared to 4-1BB (42% BCR and 70% BOR)." (PMID 39174908, 2024).
hepatocellular carcinoma (10 papers, 2019 to 2025). A malignant tumor that arises from hepatocytes. "This is in line with a study showing that IL-27 pretreatment of hepatocellular carcinoma cells resulted in lowered IL-2 production by anti-CD3/-CD28 activated T-lymphocytes." (PMID 37818353, 2023). "CD28+PD-1+ Tc cells (CD8+ T cells) constitute a dysfunctional subset of T cell; however, the mechanisms underlying their dysfunction and their significance in hepatocellular carcinoma (HCC) remain unclear." (PMID 40534863, 2025). "We selected inducible T cell costimulator (ICOS) rs4404254 T>C, rs10932029 T>C, CD28 rs3116496 T>C and CD80 rs7628626 C>A SNPs and assessed the potential relationship of these SNPs with hepatocellular carcinoma (HCC) risk." (PMID 31235485, 2019). "Meanwhile, the immunosuppressive function of LAMP3+ DCs has been validated in hepatocellular carcinoma (HCC) and non-small-cell-lung cancer (NSCLC) where LAMP3+ DCs showed strong interaction with exhausted T cells, Tregs and proliferating T cells via CD28/B7 binding and IL-15 signaling." (PMID 34568077, 2021). "In NSCLC and hepatocellular carcinoma (HCC), the inhibition of PD-1 on tumor CD103+CD8+ T cells stimulated with anti-CD3 plus anti-CD28 antibodies enhances IFN-γ production by these cells." (PMID 37545498, 2023). "Furthermore, second-generation CARs (including CD28 costimulation) could specifically target L and HBV S antigens, and thereby enhance the T cells functions to eradicate human hepatoma cells infected with HBV." (PMID 32742489, 2020).
pancreatic cancer (10 papers, 2015 to 2025). "To more comprehensively verify the anti-tumor effect of IL15C-NKG2D-CAR T on pancreatic cancer, we will evaluate the stimulatory effects of 4-1BB and CD28 on CAR T cells separately." (PMID 40625735, 2025). "Human peripheral blood-derived T cells were sorted and activated with CD3/CD28 antibodies, whereas human peripheral blood-derived monocytes were sorted and activated with M-CSF, followed by co-culturing with pancreatic tumor organoids." (PMID 40520004, 2025). "In other studies, it was reported that cancer exosomes induce suppressor CD27- /CD28- CD8+ T-cells phenotype in head and neck cancer models and inhibit the antigen-presenting function of dendritic cells in pancreatic cancer cell line model." (PMID 39883638, 2025).
gastric cancer (9 papers, 2021 to 2026). A primary or metastatic malignant neoplasm involving the stomach. "Mendelian randomization identified immune signatures associated with altered gastric cancer risk, including increased risk from alcohol intake, CD28 on resting Treg and CD62L‐ HLA DR++ monocyte AC." (PMID 41292676, 2025). "Previous results in gastric cancer cultures demonstrated that the effect of the PD-1 inhibitor nivolumab can be enhanced when combined with immune activators (e.g., CD3/CD28 T-lymphocyte activator ImmunoCultTM), resulting in similar effect sizes to those found in the present study." (PMID 38087365, 2023).
graft versus host disease (9 papers, 2012 to 2024). An immune system disorder that occurs after allogeneic hematopoietic stem cell transplant and is a reaction of donor immune cells against host tissues. "Furthermore, CD28-KO T cells could mediate skin allograft rejection, acute lethal graft-versus-host disease, and diabetogenic responses in NOD mice." (PMID 26276872, 2015). "Our study investigated the potential of peripheral blood T cell CD25, CD28, and CTLA-4 gene transcription levels as predictive biomarkers for acute graft-versus-host disease (aGVHD) following allogeneic hematopoietic stem cell transplantation (allo-HSCT)." (PMID 39072333, 2024). "TSCM cells, featured by CD45RA+ CD45RO− CD27+ CD28+ CCR7+ CD62L+ CD95+ CD122+ CD127+, were first discovered in mouse models of human graft versus host disease (GVHD) in 2005 and isolated in vitro in 2013." (PMID 38049832, 2023). "Recent works have proposed using anti-CD3/anti-CD28-based protocol to activate naïve TLs from peripheral blood in CMV infection and graft versus host disease (GVHD) contexts." (PMID 34566953, 2021). "Similarly, in a chronic graft versus host disease (GVHD) model of SLE generated by transfer of splenocytes from 6.C-H2bm12/KhEg mice into BL6 or BL6 miR-21−/−, lack of miR-21 showed a drastic reduction in autoantibody titers, CD40:CD40L and CD28:CD80/86 stimulation signals." (PMID 30322050, 2018).